WDFY3-AS2 (WDFY3 antisense RNA 2)
Synonyms: FBI4; C4orf12; NCRNA00247
Gene: Long non-coding RNA gene on chromosome 4 (84,965,534 to 85,011,277, forward strand). Ensembl gene ENSG00000180769.
Diseases named in the same sentence as WDFY3-AS2 in open-access papers:
WDFY3-AS2 is named in the same sentence as 1 disease in open-access papers, as found by Europe PMC text mining. Sharing a sentence is not in itself a finding about the gene and the disease.
WDFY3-AS2 shares sentences with these, for which no sentence is quoted: glioma (1 paper).